STAT2 (signal transducer and activator of transcription 2)
Diseases named in the same sentence as STAT2 in open-access papers (continued):
Sharing a sentence is not in itself a finding about the gene and the disease.
infection (continued). "T. gondii infection, moreover, does not elicit type 1 IFNs and their potential disease-exacerbating comorbidities; a phenomenon observed in the course of many infections and an important consideration, particularly in the context of STAT2 deficiency and hence disrupted type 1 IFN signaling." (PMID 27780205, 2016). "Consistent with STAT1 and STAT2 activation, they also observed an increased abundance of genes encoding downstream targets of interferon signalling in response to infection, including the interferon regulatory factor 1 gene, located in the 5q31q33 chromosomal region." (PMID 20657648, 2010). "In the absence of IFNβ signaling, studies have observed reduced levels of STAT1, STAT2, IRF1, and IRF7 in cells maintained in sterile environment, making them less responsive to interferon signaling and more susceptible to subsequent infection." (PMID 41525418, 2026). "Consistently, physalin F inhibited SeV-induced phosphorylation of IRF3 at Ser386 (IRF3S386), STAT1 at Y701 (STAT1Y701), and STAT2 at Y690 (STAT2Y690) at 8 h post-infection in HEK293T cells." (PMID 41599057, 2026). "Intriguingly, in H1299 cells, IRF9 and STAT2 expression was significantly reduced under both treatments when E1B-55K was present during infection." (PMID 41183090, 2025). "This mouse model significantly advances the study of JEV pathogenesis, the therapeutic evaluation of this infection and the role human STAT2 has in neuroinvasion and immune evasion." (PMID 40855992, 2025). "STAT1-/-STAT2-/-mice succumb in early infection, indicating the resistance of the STAT1/2-mediated IFN signalling pathway to DENV-2 (strains S221, 16681, D2S10) infection." (PMID 39312399, 2024). "Crucially, although our data have demonstrated that mutations at residue K28 attenuated the efficiency of ZIKV to antagonize STAT2, it was only evaluated in an infection model comprising A549 cells with competent and defective IFN-I-signaling." (PMID 38674605, 2024). "The expression levels of all genes except Stat2 and Stat3 increased rapidly from 0 to 4 h and peaked at 12 h after infection, with a subsequent gradual decrease until 16-h post-infection." (PMID 38753026, 2024). "We measured STAT2 degradation following infection with ZIKV and DENV, and as expected, both viruses induced the degradation in H. sapiens STAT2 in control Huh-7.5 cells." (PMID 38926343, 2024). "This indicates that the observed phenotype of STAT1 and STAT2 cleavage and degradation in SVA infection is caused by 3Cpro." (PMID 38869319, 2024). "In line with the suppression of the type I interferon response, TPF treatment led to a reduction in the activation (indicated by phosphorylation) of both STAT1 (signal transducer and activator of transcription 1) and STAT2, observed 24 h post-infection." (PMID 38932212, 2024). "To determine the effect of C. sorokiniana in HT-29 cells, we studied the mRNA levels of IFN-γ, IL-10, SOCS3, STAT1, and STAT2 genes in cells incubated with C. sorokiniana in the rotavirus pre- and post-infection assays." (PMID 38791551, 2024). "In TFs-mRNA network, JAK2 and STAT2 mediate the signal transduction of more than 50 cytokines and growth factors in many different cell types, which is critical for resisting infection and enforcing barrier functions." (PMID 36969251, 2023). "In this study, the STAT2 phosphorylation was inhibited 48 h after SFTSV infection in Mpf (ferret) cells." (PMID 37187292, 2023). "In contrast, murine, ferret, and porcine STAT2 were phosphorylated independently of SFTSV infection in NIH3T3 (mouse), Mpf (ferret), and PK15 (pig) cells." (PMID 37187292, 2023). "In keeping with these data, we identified the transcription factors (TF) Stat2, Irf9 and Irf8 to be upregulated in NK cells infected with VACV, these TFs are associated with NK maturation and proliferation in response to infection." (PMID 36911702, 2023). "Specifically, increased phosphorylation of STAT2 occurred at the early phase of infection with multiple viruses." (PMID 36148221, 2022).
infection (continued). "Similar to STAT1-/- or IFNAR1-/- mice, STAT2-/- mice display excessive inflammation, viral burden, and increased morbidity after infection with influenza virus." (PMID 36148221, 2022). "For instance, ZIKV-infected mice depleted of Stat2 exhibit more severe infection, as measured by survival, mobility/paralysis, and body weight as compared to Stat2-intact mice, suggesting a role of the interferon-STAT2 pathway in ZIKV pathogenesis." (PMID 35844234, 2022). "These mice are normal and immunocompetent but are susceptible to ZIKV-mediated antagonism of STAT2-mediated antiviral signaling, more faithfully modeling the human innate immune response to ZIKV-infection." (PMID 35462541, 2022). "The data exhibited that increased phosphorylation of STAT2 still appeared at early infection stage (3 hpi)." (PMID 36148221, 2022). "T403A/WT mice, in which both forms of STAT2 are expressed, responded similarly to WT/WT mice, suggesting that STAT2 phosphorylated on T403 is vital in the defense against this infection." (PMID 32759968, 2021). "This is consistent with the involvement of a specific viral protein that is transiently expressed at early time after infection in the control of STAT2 expression." (PMID 34512601, 2021). "Next, we analyzed the total expression levels of STAT1 and STAT2 in mock or ASFV infected PAM that were either mock treated or treated with IFN-I at 7 or 15 h post-infection." (PMID 34512601, 2021). "To determine the mechanisms by which STAT1 and STAT2 levels decrease during infection, we then quantified the amount of STAT1 and STAT2 mRNA in mock infected and ASFV infected PAMs." (PMID 34512601, 2021). "We infected Huh7.5-GFPu cells with C7 at an MOI of 1, treated the cells with 10 μM MG132 for 12 h at 1, 2 and 3 d post infection and then analysed the STAT2 and GFPu expression levels." (PMID 34340648, 2021). "Proteasome-dependent degradation of STAT2 has been detected during infection with Zika, Dengue, Human Cytomegalovirus (HCMV), Respiratory syncytial virus and PRRSV." (PMID 34512601, 2021). "MG132 can basically restore the expression of ubiquitinated STAT2 reduced by ZIKV at 24 h post infection, but only partially restore the expression of ubiquitinated STAT2 reduced by ZIKV at 36 h post infection." (PMID 34340648, 2021). "It was shown previously that super-infection with pathogenic S. aureus leads to the enhancement of viral titers due to the inhibition of STAT1 and STAT2 dimerization, resulting in decreased production of anti-viral factors." (PMID 33333815, 2020). "Collectively, these data suggest that STAT2 in mice represents a significant barrier to murine infection by HMPV." (PMID 32635475, 2020). "We found that level of STAT1 and STAT2 phosphorylation in IL-36γ pre-treated cells was dramatically decreased at later stages (at 24 h) of infection." (PMID 33193319, 2020). "In STAT2 KO hamsters, following infection with a Malaysia strain (P 6–740) of ZIKV via the subcutaneous route at 8.5 days post coitus results in productive infection of placental tissue and vertical transmission of infectious virus into the fetal brains." (PMID 33091001, 2020). "Here, we report that ZIKV-specific human polyclonal antibodies (SAB-155), elicited in transchromosomal bovine (TcB), provide significant protection from infection by ZIKV in STAT2 knockout (KO) golden Syrian hamsters both prophylactically and therapeutically." (PMID 30678320, 2019). "STAT2 KO Syrian hamster have shown successful infection with Zika virus (ZIKV) and the infected hamsters displayed the similar symptoms as in human." (PMID 31632404, 2019). "Starting at 24 h after infection, we observed the appearance of phospho-STAT2 (P-STAT2) and an enhanced expression of STAT2, MxA and ZIKV NS5 proteins." (PMID 31673117, 2019). "We demonstrated that both treatments with SAB-155 provide significant protection from lethal infection by ZIKV in the STAT2 KO hamster model." (PMID 30678320, 2019).
infection (continued). "Based on the PRNT50 data, sera assayed at these time-points had detectable levels of ZIKV-specific neutralizing antibody, indicating that infection can elicit a neutralizing antibody response in STAT2 KO hamsters." (PMID 30678320, 2019). "Uncontrolled virus spread is also seen following peripheral infection of mice with deficiencies in the IFN-I system and in mice expressing human STAT2, which is recognized by ZIKV and degraded." (PMID 31511023, 2019). "Collectively, we estimate the role of lymphocytes and adaptive immunity in the herein described STAT2-dependent phenotype during the first days of infection to be rather restricted at early time points." (PMID 29743368, 2018). "The expression of MyD88, STAT1, and STAT2 increased after infection with both parasites day 1 and day 4 p.i." (PMID 30327482, 2018). "Here, we report on a new RVFV inhalation infection model in STAT2 KO hamsters exposed to aerosolized MP-12 vaccine virus by nose-only inhalation that enables a more accurate delivery and measurement of exposure dose." (PMID 30463176, 2018). "Western blot analysis indicated that both ZL1and ZL1(V2634M) viruses induced STAT2 degradation at day 3 post infection, suggesting that wild type and mutant NS5 had comparable ability to antagonize innate immunity." (PMID 30002446, 2018). "Our findings, establishing a new model of aerosol RVFV MP-12 infection in STAT2 KO hamsters, demonstrate an infection with tropism for the liver and spleen consistent with observations in human cases and other RVF animal models." (PMID 30463176, 2018). "In contrast, siRNA against STAT2 in infected placenta cells significantly induced AXL expression after three days of infection when compared to control cells." (PMID 30453684, 2018). "Infection with wt-MCMV reduced STAT2 levels in wild-type cells, whereas ΔM27-MCMV lost the ability to degrade STAT2." (PMID 29743368, 2018). "Consistent with earlier reports showing CNS inflammation in ZIKV infected neonatal mice and Rhesus macaques, infection of Stat2-/- mice with all ZIKV strains led to inflammatory immune responses in the brain." (PMID 28278235, 2017). "Recent work has revealed that the NS5 protein of both MR-1947 and PR-2015 promotes the degradation of human STAT2 protein during infection, allowing ZIKV to evade type I IFN signaling downstream of the type I IFN receptor." (PMID 28152048, 2017). "ZIKV RNA measurements on day 6 post infection in the brain, ovary, spleen and liver of Stat2-/- and Ifnar1-/- mice showed the highest viral RNA levels in the brain, followed by ovary, spleen and minimum levels in the liver." (PMID 28278235, 2017). "Given the presence of uninfected cells, even at MOI of 1, it remains possible that the STAT1 and STAT2 phosphorylation observed during infection is from uninfected cells." (PMID 28152048, 2017). "Together, these results demonstrate that activation of STAT signaling molecules does not differ significantly early in infection (3 dpi), but that STAT1 and STAT2 phosphorylation occurs later infection in CD46+ and CD46+/IFNγ-KO explants." (PMID 27178303, 2016). "At first, WT- and STAT2-deficient mice were injected with IFN-γ or PBS (controls), before peritoneal macrophages were collected for ex vivo infection experiments with T. gondii tachyzoites." (PMID 27780205, 2016). "Here, we demonstrate that the Type I IFN pathway is disrupted in STAT2 KO hamsters, which makes these animals extremely sensitive to intravenous infection with Ad5." (PMID 26291525, 2015). "From 26 h post infection onwards STAT2 abundance increased again, most likely due to continued growth of uninfected cells expressing normal levels of STAT2 (~40% as deduced from the infection efficiency of cells that had not been treated with IFN)." (PMID 26720415, 2015).
infection (continued). "A robust innate immune response, with expression of Stat2 and other anti-viral factors, and a modest antibody response, occurs late in infection (9 to 11 days-post-infection (dpi)) before death occurs." (PMID 25856432, 2015). "In agreement with earlier reports, Western blot analysis revealed rapid STAT2 degradation that was detectable already 6 h after infection." (PMID 26720415, 2015). "To correlate DENV replication and STAT2 degradation, we infected A549 cells with the virus and harvested the cells right after inoculation up to 96 h post infection." (PMID 26720415, 2015). "Nonetheless, a recent report has showed that infection of DCs with L. amazonensis amastigotes resulted in alteration of the STAT-2 pathway, with a concomitant reduction in the production of IL-12." (PMID 25255446, 2014). "We were unable to achieve the high levels of infection (>90%) required for looking at total STAT1/STAT2 phosphorylation in infected cells with any virus except RPV-Sa." (PMID 23431397, 2013). "Infection with DENV decreases type I IFN-mediated STAT1 phosphorylation and also causes a proteasome-dependent decrease in STAT2 protein levels." (PMID 22590678, 2012). "Exploiting the intrinsic host-shut-off mechanism of VACV, thereby blocking STAT2 neo-synthesis, we quantified STAT2-HA amounts upon infection with wt-VACV in comparison to M27-Flag-VACV in presence and absence of MG132." (PMID 21698215, 2011). "At 12, 18, and 24 hours post-infection, the high viremia observed in the single- and double-deficient strains (all p<0.0005) demonstrates that the combined function of both STAT1 and STAT2 is required for effective control of viral replication." (PMID 21379341, 2011). "DNA from S221-infected wild type, STAT1−/− and STAT1−/−/2−/− BMMs was harvested at 12 and 24 hours post-infection, and quantitative PCR was performed on anti-STAT2 precipitated DNA using primer pairs specific to ISREs located in the promoters of these genes." (PMID 21379341, 2011). "Consistent levels of STAT1 phosphorylation were detected at all time points in wild type cells, whereas levels of phosphorylated STAT2 were highest at 12 hours after infection and decreased over time." (PMID 21379341, 2011). "This suggests that early control of DENV replication requires the combined function of STAT1 and STAT2, but STAT2-independent mechanism(s) begin to restrict replication by 24 hours post-infection." (PMID 21379341, 2011). "Hahm and colleagues showed that dendritic cell maturation is impaired in a IFN-β-dependent, STAT2-dependent manner following infection of pluripotent bone marrow cells by measles virus (MV) and LCMV." (PMID 21379341, 2011). "Importantly, infection with LSDV122-deficient virus (LSDVΔ122) enhanced IFN-β-induced phosphorylation of STAT1 and STAT2, as well as transcription of downstream antiviral ISGs compared to wild-type LSDV." (PMID 41525414, 2026). "Interestingly, during infection, orbiviruses induce autophagic degradation of STAT2 to replicate in cells." (PMID 41262030, 2025). "STAT2 was phosphorylated only under infection conditions in H820 cells." (PMID 40434103, 2025). "Of note, STAT2 levels decreased upon infection of H322 cells." (PMID 40434103, 2025). "Therefore, we transfected RAW264.7 cells with STAT1 and STAT2 specific siRNAs, followed by infection with RSV." (PMID 40245000, 2025). "Additionally, MGF505-4R was able to coprecipitate with STAT1 and STAT2 during infection with ASFV-WT." (PMID 40618140, 2025). "Similarly, phospho-STAT1 and phospho-STAT2 levels were increased in UL26ΔC-infected cells relative to mock or WT infection." (PMID 38768227, 2024). "Interestingly, we observed the downregulation of genes such as Tnf-α, Il18, Mx1, Rig1, Pkr, Stat1, Stat2 and Irf9, which appear to be hallmarks of hRSV persistence in contrast to the acute infection." (PMID 39296294, 2024). "For STAT2 “GOF”, early treatment of infections may help to mitigate the risk of subsequent severe hyperinflammation." (PMID 39599507, 2024).
infection (continued). "To investigate this possibility, we wanted to determine whether infection with HAdVs differentially affects STAT2 levels and ubiquitination." (PMID 38940561, 2024). "In agreement with others, STAT2 degradation in the A549 cell line occurs rapidly after infection." (PMID 38384473, 2024). "This may indicate that the antiviral response induced by C. sorokiniana in rotavirus-infected cells was mediated by IFN-α and IFN-γ in the pre-infection assays and STAT1/STAT2 in the post-infection assays and regulated by SOCS3 in both assays." (PMID 38791551, 2024). "Moreover, the involvement of the “type I interferon signaling pathway” with genes like IRF7 and STAT2 highlights the role of interferon responses in modulating the immune landscape during the later stages of infection." (PMID 38957806, 2024). "A combination of B. longum and C. sorokiniana was used to study its effect on the antiviral response in HT-29 by measuring the mRNA levels of IFN-γ, IL-10, SOCS3, STAT1, and STAT2 genes in cells with the combination of B. longum/C. sorokiniana in the pre- and post-infection assays with rotavirus." (PMID 38791551, 2024). "Pretreatment with IFN-α2B for 16 hours before HSV-1 infection significantly decreased viral replication levels relative to untreated cells 72 hours after infection in healthy control cells, but not in STAT2-, IFNAR1-, STAT1-, and IRF9-deficient cells." (PMID 36976641, 2023). "Moreover, we detected a modest but statistically significant reduction in the levels of STAT2 protein after M81wt infection." (PMID 37830871, 2023). "In addition, Ddx58 and cGAS, which encode factors for virus sensing, Stat1, Stat2, and IFN regulatory factor 7 and 9 mRNA levels were also induced at the initial stage of infection." (PMID 38125412, 2023). "Similarly, GPB2 and STAT2 transcription were induced more in IRF3-transfected cells during OC43 infection." (PMID 37197656, 2023). "It was found that early activation of STAT2 was also induced by infection of MDRV." (PMID 36148221, 2022). "However, the STAT2 Y690 phosphorylation declined at the late hpi in the cells infected by various strains of IAV except infection with H9N2." (PMID 36148221, 2022). "Sustained activation of STAT2 even at 24 hpi following H9N2 infection may be related to the subtype or virulence of the strain." (PMID 36148221, 2022). "Thus, in IFN-I-stimulated cells, STAT2 levels in the cytoplasm were higher during the infection compared to the mock samples, whereas in the nuclear chromatin-binding fraction (P3), a marked decrease of STAT2 was observed." (PMID 36713190, 2022). "In addition, downregulated phosphorylation of STAT1 and STAT2 were observed in ISG15-/- mice after infection with PRV in vivo." (PMID 36146669, 2022). "However, hyperactive STAT2 expression can lead to lung damage during infection, including most recently from SARS-CoV-2 infection." (PMID 34662402, 2022). "Taken together, these data demonstrated that initial activation of STAT2 could be induced by infection of several types of viruses in various cell lines." (PMID 36148221, 2022). "The results showed that phosphorylation of STAT2 Y690 appeared in cells at 3 hpi by WSN infection but was not caused by lysates of cells infected with the IAV (WCL) and cell culture supernatant (SN)." (PMID 36148221, 2022). "Interestingly, initial activation of STAT2 was also detected upon infections with several other viruses such as dsRNA virus MDRV, and DNA virus PRV." (PMID 36148221, 2022). "We analysed the protein levels STAT2 at 48 and 72 h post infection." (PMID 34340648, 2021). "Interestingly, under these experimental conditions, we found that STAT2 levels were drastically affected during Arm/07/CBM/c2 infection at 16 hpi." (PMID 34512601, 2021). "Therefore, it is likely that observed STAT2 degradation is induced at very early times of the infection, prior to viral DNA replication." (PMID 34512601, 2021).